BDNF (brain derived neurotrophic factor)
Diseases named in the same sentence as BDNF in open-access papers (continued):
Sharing a sentence is not in itself a finding about the gene and the disease.
depression (continued). "However, previous animal studies have indicated that an increase in BDNF signalling in the VTA-nucleus accumbens system may be related to depression." (PMID 25739024, 2015). "This study investigated whether BDNF methylation is a marker of depression." (PMID 26285129, 2015). "More importantly, we intended to investigate whether the antidepressant effect of Shuyu is mediated by MOR, and the depression-associated signal molecules, that is, CREB (cAMP response element binding protein), BDNF (brain derived neurotrophic factor), MEK, and ERK." (PMID 25821488, 2015). "In addition, EA changed the serum BDNF in the opposite direction of depression and pain." (PMID 25947167, 2015). "However, based on the present data, and on our subsequent meta-analyses on peripheral BDNF in schizophrenia and in major depressive disorder, it seems clear that peripheral BDNF levels are not useful as a diagnostic biomarker in psychiatric disorders because of lack of specificity." (PMID 26621529, 2015). "In human subjects, it has been shown that BDNF increases after physical exercise, and this increase may correlate to improvement of cognitive functions in pathological conditions such as stroke and depression." (PMID 25852518, 2015). "The expression of BDNF is also reduced in the hippocampus and prefrontal cortex of serotonin transporter knockout rats, a genetic model of depression and anxiety, suggesting that changes of neuronal plasticity may also contribute to the genetic susceptibility to mood disorders." (PMID 25873859, 2015). "Finally, there are marked similarities in terms of neurobiology, brain-derived neurotrophic factor (BDNF) levels being reduced in both states; in this study BDNF levels were further reduced in the people with bipolar disorder compared to those with unipolar depression." (PMID 26459976, 2015). "The direct action of riluzole evoking BDNF release from human platelets at therapeutic concentrations is important and may contribute to the understanding of its mechanisms of action in the treatment of depression." (PMID 25629040, 2015). "We hypothesize that serum BDNF levels do not decrease in MDD patients with high HA or low SD because these traits may enhance susceptibility to depression even in the absence of biological changes." (PMID 25885038, 2015). "However, human studies are only correlative and a clear causal association between impairment of BDNF brain activity and depression has not been yet demonstrated in human patients." (PMID 25386150, 2014). "Since both BDNF and glucocorticoids may be involved in neuronal function as well as the pathophysiology of depression, a possible crosstalk between BDNF and glucocorticoid function has been proposed as one of the mechanisms for depression." (PMID 24550703, 2014). "By contrast, there is no consensus as to whether decreases in BDNF activity cause depression-like behavior in mice since the results vary between different studies." (PMID 24817844, 2014). "Therefore, the current hypothesis, suggesting a strong link between low BDNF brain levels and depression, appears to be too simplistic and has to be reconsidered." (PMID 25386150, 2014). "Moreover, BDNF is potentially involved in stress-related mood disorders, e.g., major depression." (PMID 25383981, 2014). "Memory bias may not be strongly associated with the PCLO rs2522833 polymorphism, unlike other genes that have been associated with depression (e.g. BDNF, NR3C2)." (PMID 25379724, 2014). "As NPY and VGF also actively participate in the neurotrophic hypothesis of depression and could be regulated by BDNF, our data argue that both BDNF and its downstream neurotrophic peptides, NPY and VGF, may play a role in the antidepressant effects of exercise." (PMID 25477997, 2014).
depression (continued). "It has been suggested that BDNF may be differentially involved with specific aspects of depression symptoms; accordingly, the coping profiles and behavioral training used in the current study provide an opportunity for systematic investigations of several measures of neuroplasticity." (PMID 24808837, 2014). "Next, we conducted linear regression analyses using the anxiety/depression variable as the outcome and the mother’s positive feelings about caring for her baby as the predictor within each genotype; thus, separate models were created for subjects with the BDNF Val/Val and other genotypes." (PMID 25425456, 2014). "Thus, it is likely that decreased levels of BDNF in the DG and CA3 of the hippocampus and in the PFC, as well as increased levels of BDNF in the NAc, may promote depression-like behavior in rodents." (PMID 25628381, 2014). "At this time there is ample reason to suggest that particular cytokines (e.g., IL-6) and growth factors (e.g., BDNF) might serve as biomarkers in predicting who would be most prone to depression under various challenge conditions, and which treatment strategies would be most efficacious." (PMID 23675319, 2013). "However, the implication of TrkB in depression pathophysiology bears more complexity because the TrkB gene in addition to the active full length isoform has a truncated isoform which modulates negatively BDNF signaling." (PMID 24222865, 2013). "As briefly mentioned earlier, additional support for the possibility that impairments of neurogenesis may promote depression has come from a series of reports indicating that stressors elicit peripheral and central variations of growth factors, especially that of BDNF." (PMID 23675319, 2013). "Thus, these independent studies suggest that the serum BDNF levels could be utilized as a surrogate biomarker of depression." (PMID 23704927, 2013). "Finally, BDNF may be an important mediator of the previously noted HPA axis effects on depression and cardiovascular disease." (PMID 23653854, 2013). "Finally, the Pearson’s (or Spearman’s) correlation coefficient was calculated to study whether there was a relationship among the Self-Rating Depression Scale score, the serum BDNF levels, and serum BDNF-related miRNA levels." (PMID 23704927, 2013). "Collectively, we provided evidence supporting that miR-182 is a putative BDNF-regulatory miRNA, and suggested that the serum BDNF and its related miRNAs may be utilized as important biomarkers in the diagnosis or as therapeutic targets of depression." (PMID 23704927, 2013). "However, injection of BDNF into the dopamine pathway of mesolimbic system could elicit depression-like response." (PMID 24363618, 2013). "When BDNF binds to its high affinity receptor TrkB, it is retrogradely transported to the cell body where it promotes biological effects to enhance synaptic contacts as well as neuronal plasticity, neurotransmission, and neurotrophic factor synthesis leading to control of depression." (PMID 24367385, 2013). "First, since anxiety disorders and depression are highly comorbid and there is evidence for lower BDNF in depression, the inclusion of patients with depression in some of the studies may partially account for the reduced plasma BDNF levels in the patient sample." (PMID 23908608, 2013). "In this study, we investigated whether the Val66Met polymorphism and serum BDNF levels are different in Han Chinese subjects who suffered from T2DM with or without depression." (PMID 23968401, 2013). "Given the high level of comorbidity between depressive and anxiety disorders, and the similarities in their pathophysiology, it is plausible that BDNF levels in anxiety disorders may mirror the changes found in depression and potentially serve as a peripheral biomarker." (PMID 23908608, 2013).
depression (continued). "More recent epidemiologic studies showing T2DM patients develop more depression and at the same time have lower serum BDNF levels compared to non-diabetic individuals, posed an interesting question whether the higher rate of depression in diabetes may be in part mediated by decreased BDNF levels." (PMID 23968401, 2013). "It seems that medication-free depressed patients may exhibit a unique profile in which activation of particular pro-inflammatory cytokines (especially that of IL-6) and reductions of growth factors (especially that of BDNF) are inversely related to the severity of depression." (PMID 23675319, 2013). "In addition to the previous mechanisms, BDNF may also play an important role in the connection between depression and cardiac outcomes." (PMID 23653854, 2013). "This said, the data concerning peripheral BDNF in relation to stressor effects in humans have been inconsistent, and what these differences might mean with respect to subsequent neurogenesis, neuroplasticity, and depression, remain to be clarified." (PMID 23675319, 2013). "Our results showed that depression-like changes were accompanied by alterations in several depression-related parameters, including elevation of oxidative stress, reduction of plasma levels of BDNF and serotonin, and attenuation of intracellular BDNF/TrkB-mediated signaling." (PMID 24367510, 2013). "Thus, the relationships among BDNF, 5-HT, and depression remain controversial." (PMID 23593198, 2013). "Therefore, it would be beneficial to especially quantify individual levels of pro- and mature BDNF to reveal if reduced levels of total serum BDNF are driven by an imbalance of either pro- or mature BDNF, which was already shown for patients suffering from major depression." (PMID 24146812, 2013). "Although there have been several comparable reports, it has also been shown that the presence of the Met allele might not necessarily lead to BDNF reductions that dispose individuals to depressive disorders." (PMID 23675319, 2013). "The discovery of a possible relationship between the BDNF and MDD meant a great advance in the understanding of the neurobiology of depression." (PMID 23204984, 2012). "The aims of this study were to evaluate whether monoaminergic reuptake inhibition increases BDNF in vivo and in vitro as predicted by the neurotrophic hypothesis of depression, and whether triple reuptake inhibition has a superior BDNF response compared to dual reuptake inhibition." (PMID 22581450, 2012). "It is reasonable to believe that miR-16 may play a crucial role in the development of depression via simultaneously modulating the expression of multiple genes with different physiological functions, such as BDNF’s role in neurogenesis and BCL-2′s involvement in neuron survival and apoptosis." (PMID 23056528, 2012). "Thus, concomitant depression could mask a possible inflammatory BDNF overproduction in patients with severe COPD." (PMID 23245944, 2012). "In addition,BDNF reduction-mediated decrease in neuronal plasticity is sustainable, and the depression-related neurobiological anomaly may be hard to be reshaped to normal state." (PMID 23056528, 2012). "Furthermore, stress, a trigger for depression, lowers hippocampal transcription of BDNF in mice." (PMID 21799699, 2012). "Given the fact that the stress-induced alterations in hippocampal BDNF expression and depression-like behaviors varied with different stressors, we tested our hypothesis in this study with two classical chronic stress paradigms: maternal deprivation (MD) and chronic unpredictable stress (CUPS)." (PMID 23056528, 2012). "Mean methylation rates of CpG 1 but not 4 at the BDNF promotor was associated with depression." (PMID 22738307, 2012).
depression (continued). "Decrease in the volume of the hippocampus and other prosencephalic structures in subgroups of depressed patients supports the hypothesis of decrease of neurotrophic factors in depression, especially the BDNF, which is profusely expressed in the adult limbic system." (PMID 23204984, 2012). "Several results suggest that BDNF may play a protective role in the pathophysiology of depression." (PMID 21799699, 2012). "BDNF is a neurotrophic substance (it promotes the growth and survival of neurons) and there is considerable evidence that the levels of BDNF in the brain decrease during depression and, in theory, this could lead to atrophic brain changes, especially in the hippocampus." (PMID 23204984, 2012). "We therefore hypothesize that: 1) Environmental stressors may induce miR-16 expression; 2) High miR-16 expression may downregulate BDNF expression; and 3) Downregulation of BDNF expression may lead to the reduction of hippocampal neurogenesis and subsequent depression-like behaviors." (PMID 23056528, 2012). "The previous findings raise the possibility that a lack of BDNF or a lack of neurogenesis in the hippocampus might cause depression." (PMID 22912626, 2012). "Since it is also known that patients with MDD suffer cognitive impairment even in remission, we examined the correlation between serum levels of proBDNF, mature BDNF, and MMP-9, with clinical variables, including depression and cognition, in patients with MDD." (PMID 22880079, 2012). "The neurotrophic hypothesis of depression and antidepressant action arose from evidence suggesting that BDNF levels are reduced in mood disorders and that chronic antidepressant treatment enhances BDNF expression and signaling." (PMID 22563458, 2012). "This important observation suggests that the biological backgrounds of patients with treatment-responsive MDD and patients with treatment-resistant MDD might differ, and that high plasma BDNF levels during the depressive syndrome stage may be indicative of treatment-resistant MDD patients." (PMID 22761741, 2012). "Thus, we propose that the DNA methylation profiles at CpG I of the BDNF gene could be a valid biomarker for the diagnosis of major depression." (PMID 21912609, 2011). "Interestingly, it has been suggested that interferon-induced immune activation on depression may be explained in part by alterations in neurotrophin signaling capacity, reflected by decreases in serum BDNF following interferon treatment." (PMID 21857948, 2011). "It has indeed been proposed by some authors that the therapeutic use of BDNF itself or of drugs targeting its production may constitute a valid alternative to treat depressed patients with cognitive impairment or AD concomitant with depression." (PMID 22654714, 2011). "BDNF, and its receptor TrkB, are also required for the anti-depressant effect of imipramine and fluoxetine in rodent models, suggesting that neurotrophin therapy may also have beneficial effects in post-traumatic stress and other depressive disorders." (PMID 19090982, 2008). "In addition, it has recently been suggested that the anti-inflammatory role of omega-3 fatty acids may influence brain derived neurotrophic factor (BDNF) in depression." (PMID 15535884, 2004). "Level of depression; daily life function; and serum levels of CREB1, BDNF, and 5-HT.Results: significant." (PMID 41562835, 2026). "One study demonstrated that FA reduced LPS-induced depression-like behaviors in mice by regulating IDO, BDNF, and inflammation-related factors." (PMID 41535967, 2026). "Anti-oxidant potential In olfactory bulbectomy (OB)-induced depression models, XYS reversed behavioral deficits and oxidative stress by activating the PI3K/Akt-Nrf2/BDNF pathway." (PMID 41535967, 2026). "These benefits are primarily mediated through activation of BDNF-TrkB signaling, leading to reduced ROS/H2O2 accumulation and alleviation of CRS-induced depression-like behaviors." (PMID 41596198, 2026).
depression (continued). "PF significantly alleviated LPS-induced depression-like behaviors, increased hippocampal neuron and dendritic spine density, and upregulated synaptic proteins (PSD95, SNAP25, and BDNF)." (PMID 40427467, 2025). "Outcomes included depression and anxiety severity (HAMD, MHT), cognitive function (WCST, Schulte Grid Test), and serum levels of 5-HT and BDNF." (PMID 41477617, 2025). "For instance, reduced levels of BDNF and increased methylation of the SLC6A4 gene promoter have been notably correlated with the occurrence of major depression or a history of depression in patients with TLE." (PMID 39858450, 2025). "Our study's strength lies in the inclusion of a comparison group and the estimation of serum BDNF and IL-1β levels in conjunction with HDRS scores, which provide a more robust assessment of depression severity." (PMID 40904969, 2025). "Progesterone increases the population of lactobacilli, affecting brain function by modulating gut microbiota and upregulating the expression of brain-derived neurotrophic factor (BDNF) genes, thereby alleviating depression and anxiety during menopause." (PMID 40364840, 2025). "In the depression model, MSC activated 5‐HT neurons in the dorsal raphe nucleus, largely via BDNF‐TrkB signaling of sensory neurons in the nodose ganglia." (PMID 40874463, 2025). "The study found that exercise significantly increased circulating levels of brain-derived neurotrophic factor (BDNF) and kynurenine while reducing depression symptoms compared to the control groups (da Cunha, Feter, Alt, & Rombaldi, 2023)." (PMID 40665827, 2025). "Previous clinical evidence has reported an inverse relation between peripheral BDNF and mood symptoms: when BDNF increases, lower depressive scores in the Beck Depressive Inventory (BDI) and Hamilton Rating Scale for Depression (HDRS) can be observed." (PMID 40943216, 2025). "BDNF can affect many signaling pathways, among which ERK has been found to be a downstream signaling molecule for BDNF in depression research." (PMID 39609371, 2025). "P. gingivalis LPS activates astrocytes, which inhibits brain-derived neurotrophic factor (BDNF) maturation and promotes depression." (PMID 40843171, 2025). "In this study, we demonstrated that BTS mitigated depression-like behaviors in HFD-induced obese mice, mediated in part through the regulation of systemic/neuroinflammation, BDNF signaling, hippocampal NMDARs, and intrasynaptic 5-HT levels." (PMID 41244820, 2025). "In depression, it restores phospholipid and tryptophan metabolism, regulates HPA axis function, and increases BDNF expression." (PMID 40708436, 2025). "For instance, Hyperoside significantly mitigates depression-like behaviors in chronic stress-induced mice by inhibiting the NLRP1 inflammasome and modulating the CXCL1/CXCR2/BDNF signaling pathway, leading to improved anhedonia and reduced immobility time." (PMID 40444002, 2025). "In the combined sample, BDNF negatively correlated with past drinking (aTLFB), AUD severity, and depression measures." (PMID 40317574, 2025). "Depression-like behaviors (less immobility time, lethargy); Depression reversed by antibiotic and reproduced by FMT; Supressed cAMP/CREB/BDNF signaling." (PMID 41246320, 2025). "The therapeutic targets of quercetin for anxiety and depression are multi-faceted, encompassing the HPA axis, neurotransmitter systems, and BDNF, which underscore its multi-targeted and multi-modal treatment profile." (PMID 40520201, 2025). "A depression signature (ρ = 0.19; P = .02) differentiated ROD from HC individuals with elevated IL-1β, IL-2, IL-4, S100B, and BDNF and GMV reductions in limbic regions." (PMID 41405910, 2025).